VCF1 (VCP nuclear cofactor family member 1)
Synonyms: FAM104A; FLJ14775
Tractability: No criterion of Open Targets' tractability assessment is met for any kind of drug.
Gene: Protein-coding gene on chromosome 17 (73,207,353 to 73,236,753, reverse strand). Ensembl gene ENSG00000133193.
Subcellular location (Human Protein Atlas): Nucleoplasm; Cytosol
Gene Ontology:
Molecular function: protein binding
Genetic constraint (gnomAD): Loss-of-function variants: 12 observed, 10.99 expected, observed/expected ratio (o/e) 1.09, 90% interval 0.7 to 1.72. The upper end of that interval is the gene's LOEUF score, 1.72, which puts it in group 6 of 6, group 1 being the genes least tolerant of losing a copy. Missense variants: 226 observed, 182.17 expected, observed/expected ratio (o/e) 1.24, 90% interval 1.11 to 1.38. Synonymous variants: 82 observed, 68.14 expected, observed/expected ratio (o/e) 1.2, 90% interval 1.01 to 1.45.
Homologues: Orthologues: chimpanzee VCF1 (99% identical), macaque VCF1 (98% identical), rabbit VCF1 (89% identical), dog VCF1 (88% identical), pig VCF1 (78% identical), rat Vcf1 (78% identical), Drosophila melanogaster CG31898 (12% identical).
Diseases named in the same sentence as VCF1 in open-access papers:
VCF1 is named in the same sentence as 9 diseases in open-access papers, as found by Europe PMC text mining. Sharing a sentence is not in itself a finding about the gene and the disease. The quoted sentences say what the papers report.
cancer (1 paper, 2023). A tumor composed of atypical neoplastic, often pleomorphic cells that invade other tissues. "Moreover, the potential link between VCF1/2 and p97-mediated DNA damage repair suggested by our data could hint to a role of VCF1/2 in p97-dependent cancer cell survival, an area of intense biomedical research efforts." (PMID 37713320, 2023).
VCF1 also shares sentences with these, for which no sentence is quoted: adenocarcinoma (1 paper); Alzheimer disease (1); amyotrophic lateral sclerosis (1); Azoospermia (1); infertile (1); neurodegenerative disease (1); squamous cell carcinoma (1); tumor (1).